ALB (albumin)
Diseases named in the same sentence as ALB in open-access papers (continued):
Sharing a sentence is not in itself a finding about the gene and the disease.
malnutrition (continued). "Studies had reported that nutritional deficiency status (low albumin level) was associated with the frequency and severity of infection." (PMID 32375730, 2020). "So, cAG is greater than AG, particularly in a population of patients with a high risk of hypoalbuminemia, as is the case for patients in intensive care or patients with malnutrition, hepatopathy, chronic inflammation, or urinary loss of albumin." (PMID 31418093, 2019). "Malnutrition increases the risk of surgical-site infection, pneumonia, and urinary tract infection, and serum ALB is the most well-established serum marker of malnutrition." (PMID 30918528, 2019). "The low-to-normal mean serum albumin level (3.5 ± 0.5 g/dL) also indicated that many patients were at high risk of malnutrition." (PMID 30678632, 2019). "Low serum albumin level, as an indicator of malnutrition status, is associated with survival outcomes in EC." (PMID 31783812, 2019). "The analytical results of this study demonstrated an association between SCLs and malnutrition (serum albumin level < 3.6 g/dL) in MHD patients." (PMID 31382911, 2019). "We also collected basic malnutrition measures as weight loss before treatment and baseline albumin level as known prognostic factors." (PMID 30791870, 2019). "Low serum albumin was an excellent assessment tool for malnutrition, which was associated with poor wound healing and infection." (PMID 31253199, 2019). "The symptomatic period of the disease is usually associated with an advanced stage, where malnutrition and chronic anemia are often noticed and confirmed by a decrease in Hb and albumin levels." (PMID 31827513, 2019). "We also found an association between frailty and markers of malnutrition (serum albumin and prealbumin)." (PMID 31234684, 2019). "When it comes to laboratory studies, lower hemoglobin and albumin levels have long been linked to inflammation and malnutrition." (PMID 31419960, 2019). "Serum albumin is closely correlated with the degree of malnutrition, considered a general risk factor in critically ill conditions." (PMID 31565439, 2019). "A low serum albumin level is regarded to indicate malnutrition status, and hypoalbuminemia has been associated with reduced LVEF and LV hypertrophy in patients with heart failure." (PMID 31781303, 2019). "In the logistic regression analysis performed in this study, malnutrition, defined as a serum albumin level < 3.5 g/dL, was significantly associated with dysphagia." (PMID 31852457, 2019). "Recovery of albumin level is important after chemotherapy because nutrition deficiency is higher in advanced stage of cancer patients with malnutrition." (PMID 30941358, 2019). "Serum albumin levels can be an indicator of malnutrition that in turn is associated with impaired immune response in cancer patients." (PMID 31788452, 2019). "Decreased serum albumin concentration due to reduced albumin synthesis caused by malnutrition and cancer induced inflammation has been described as an independent prognosticator of survival in various malignancies." (PMID 31819103, 2019). "In critically ill patients, CRP/ALB ratio reflects both inflammatory activation and nutritional deficiency, and has gradually been accepted as an emerging prognostic marker of morbidity and mortality." (PMID 31821367, 2019). "Pre-operative malnutrition and serum albumin levels are known to be associated with increased morbidity and mortality, and improving pre-operative nutrition for 7–14 days prior to surgery improves outcomes." (PMID 31100877, 2019). "Malnutrition assessed either by subjective global assessment (SGA) or by serum albumin in PD patients is associated with a statistically significant increase in mortality." (PMID 30445969, 2018). "Albumin or weight loss > 10% in the 6 months preceding surgery, both of which are indirect indicators of malnutrition before the intervention, also appear in different models." (PMID 29378647, 2018).
malnutrition (continued). "Correlation between fatigue and nutritional status is supported by the correlation between fatigue and the symptom “loss of appetite” in EORTC QLQ-C30 and low serum albumin, which represents a surrogate serum parameter of malnutrition." (PMID 30054708, 2018). "Other studies reviewing and/or defining malnutrition by low transferrin, total lymphocyte count or albumin also describe the following associated complications in arthroplasty: wound complications, extended length of stay and periprosthetic joint infection." (PMID 29544497, 2018). "Changes in serum albumin levels are relatively unspecific although hypoalbuminemias are observed in animals with malnutrition or deficient protein absorption (Kaneko, Harvey & Bruss, 2008)." (PMID 30402353, 2018). "Change in body weight is the most common anthropometric measure of malnutrition used, with weight loss associated with low albumin and prealbumin values after stroke." (PMID 29568480, 2018). "In this regard, serum albumin and cBMI are considered important factors associated with malnutrition among patients." (PMID 29652842, 2018). "Each of the three other malnutrition criteria used in our study (low nPCR values, low albumin, and low creatinine levels) was also associated with high NT-proBNP concentrations." (PMID 29075534, 2017). "Low serum albumin levels are associated with a risk of postoperative complications and poor survival outcomes because of malnutrition." (PMID 28925039, 2017). "The abnormally low levels of albumin observed in late stage cancer patients have been associated with malnutrition and inflammation, which suppress albumin synthesis by hepatocytes." (PMID 27974681, 2017). "Since GNRI is based on measurements of serum albumin and weight loss, it was expected that albumin (p < 0.001) and prealbumin (p < 0.05) were able to identify patients at risk of both high and low malnutrition as assessed by GNRI." (PMID 28771192, 2017). "For example, the estimated mean albumin concentration for patients at high risk of malnutrition was 3.42 (95% CI: 3.19, 3.64), 3.31 (95% CI: 3.13, 3.49), and 3.08 (95% CI: 2.84, 3.31) g/dL by NRS-2002, MNA and SGA respectively." (PMID 28771192, 2017). "In a large study of 14972 Korean cancer patients, the proportion of patients with high risk for malnutrition as defined by BMI, serum albumin, total lymphocyte count and dietary intake, increased with cancer stage." (PMID 27231951, 2016). "In univariate analysis, CRT, serum albumin concentration at consultation <3.5 g/dL, and malnutrition at surgery were significantly associated with AL." (PMID 26888783, 2016). "In one study of 60 cardiac transplant recipients at least five years post transplant, serum albumin was found to be a better predictor of underlying malnutrition than body mass index (BMI) and subjective global assessment (SGA)." (PMID 27174435, 2016). "Of note, the absolute baseline value of albumin can be influenced by preoperative hypoalbuminemia and thus malnutrition, which is an established risk factor for adverse outcomes." (PMID 26880899, 2016). "Low level of albumin is associated with malnutrition and weight loss, which results in a poor PS and increased cancer-related mortality." (PMID 26084991, 2015). "In both cohorts, low CNDP1 levels were associated with markers of poor prognosis including weight loss, malnutrition, lipid breakdown, low circulating albumin/IGF1 levels and poor quality of life." (PMID 25898255, 2015). "Other indicators of malnutrition or nutritional risk, including serum albumin and variables related to inflammation, showed a mortality RR of 2.3." (PMID 26091351, 2015). "In older patients who were classified as having type 2 diabetes, we found that BMI was positively associated with poor glycemic control while markers for malnutrition such as albumin and nPCR were inversely associated with poor control." (PMID 26645204, 2015).
malnutrition (continued). "An association between mortality and malnutrition or nutritional risk has been consistently reported in elderly subjects as assessed by BMI, weight loss, plasma levels of albumin, and food intake." (PMID 26091351, 2015). "Findings from other patient populations such as hip fracture suggest that low serum albumin indicative of malnutrition is associated with higher mortality and complication rates." (PMID 26410227, 2015). "We found that low albumin (possibly due to advanced disease, tumour cachexia or malnutrition) was associated with an increased risk of hospitalisation." (PMID 25922657, 2015). "There was no significant loss of patient body weight or significantly decreased in serum albumin level before admission to avoid potential influence of malnutrition-associated metabolic changes." (PMID 25622826, 2015). "Nutritional deficiency has been linked to inferior outcomes after RC but has been variably defined, using preoperative albumin levels, body mass index, weight loss, and sarcopenia." (PMID 26798336, 2015). "Multiple somatometric and serologic markers have been used to quantify nutritional deficiency including body mass index (BMI), weight loss, serum albumin, and skeletal muscle mass." (PMID 26798336, 2015). "More than 44% individuals of the study population was at risk of malnutrition, according to feeding difficulties, progressive depletion of weight, reduced daily calorie intake, reduced albumin and transferrin levels." (PMID 25000975, 2014). "As responses to chronic disease, causes cachexia and malnutrition (low Hb and albumin) as well as a systemic inflammation." (PMID 25279844, 2014). "The decreases in the albumin levels can be attributed to low dietary intake of proteins that is linked to low synthesis of albumin, a feature of malnutrition that is frequently observed among injection drug users presenting with and without HIV infection." (PMID 25057262, 2014). "Proinflammatory cytokines cause malnutrition by stimulating protein catabolism and by reducing albumin synthesis." (PMID 24772434, 2014). "Specifically, in logistic regression analysis, the log BCLs (OR = 2.64, 95% CI: 1.07–6.48, P = 0.035) were significantly associated with malnutrition (serum albumin levels of <3.6 g/dL) in the forward stepwise multivariate logistic regression analysis." (PMID 24428882, 2014). "When adjusting for time-dependent alterations of CRP and albumin concentrations as surrogates of inflammation and malnutrition, we confirmed the independent association between lower mortality and iron supplementation." (PMID 25462819, 2014). "PD is known to promote malnutrition and excessive loss of free amino acids, essential fatty acids, and albumin, leading to muscle wasting." (PMID 23418565, 2013). "Hypoalbuminemia is also a common marker of malnutrition and low levels of serum albumin was considered as key diagnostic criteria for malnutrition,especially in hemodialysis patients." (PMID 23506394, 2013). "This stability in low serum albumin concentrations suggests that those patients with a lower level of either electrolyte share some intrinsic factors, which cause long-standing malnutrition and sub-clinical inflammation." (PMID 24305468, 2013). "Lower serum albumin concentrations in the older group suggests malnutrition and chronic inflammation, which is also associated with hypoparathyroidism." (PMID 23865464, 2013). "Regarding the inverse relationship with albumin and hemoglobin, we interpret this as responses to chronic disease, for example, advanced cancer: it causes cachexia and malnutrition (low hemoglobin and albumin) as well as a systemic inflammation (high suPAR)." (PMID 22824423, 2012). "Hypoalbuminemia is associated with malnutrition and the decrease of protein level because liver reduces albumin production in favor of more important plasma proteins." (PMID 22574625, 2012).
malnutrition (continued). "We did not observe a strong linear association between HbA1c values and parameters of malnutrition such as albumin (r = 0.033, p = 0.14), phosphorus (r = 0.04, p = 0.025) or CRP (r = −0.002, p = 0.40)." (PMID 21625600, 2011). "Low serum levels of protein and albumin are markers of malnutrition and are associated with impaired functional status, poor outcome, and higher mortality." (PMID 22254136, 2011). "According to the International Society of Renal Nutrition and Metabolism (ISRNM), the serum albumin <3.8 g/dL was recommended as a main diagnostic indicator of malnutrition." (PMID 21714897, 2011). "Regarding to the laboratory finings of renal insufficiency with elevating BUN level and lower serum albumin in subjects, these implied the underlying malnutrition, status of volume depletion, and advanced illness." (PMID 22393343, 2011). "In univariate models prolonged LOS was associated with low serum albumin or hemoglobin, malnutrition (PG-SGA score and PG-SGA group B or C), low pretreatment FACT-G score, and suspected diagnosis of cancer." (PMID 20497581, 2010). "The aim of this study was to associate malnutrition and albumin serum levels with the occurrence of chemotherapy-induced toxicity in P plus TXN treated NSCLC." (PMID 20170547, 2010). "The aim of this study was to associate malnutrition and albumin serum levels with the occurrence of chemotherapy-induced toxicity in cisplatin plus paclitaxel chemotherapy-treated NSCLC." (PMID 20170547, 2010). "Malnutrition [defined either by body mass index (BMI) or biochemical markers such as albumin] is a well-recognized complication and an independent risk factor for increased mortality in adults with ESRD receiving maintenance HD." (PMID 18293013, 2009). "Malnourished participants had a trend of lower serum albumin concentration compared with those at risk for malnutrition (p = 0.06)." (PMID 17980023, 2007). "Regarding long-term outcomes, malnutrition, as indicated by low preoperative albumin, is a well-established risk factor for reduced survival and increased morbidity in chronic liver disease, independent of surgical insult, and its impact is particularly pronounced following abdominal surgery." (PMID 41590349, 2026). "Other potential factors could include patients’ nutritional status, indicated by laboratory markers of malnutrition, such as serum albumin levels or vitamin deficiencies, which can negatively impact wound healing." (PMID 39846031, 2025). "Compared to other screening methods, the MNA has the advantage of identifying individuals at risk of malnutrition before significant changes in body weight, BMI, or serum albumin occur, thereby enabling timely interventions and potentially improving clinical outcomes." (PMID 41551321, 2025). "Serum albumin is one of the most widely used indicators for assessing malnutrition risk." (PMID 40357040, 2025). "Low albumin values are often associated with malnutrition, inflammation or infectious disease." (PMID 40837733, 2025). "Serum albumin level indicates nutritional statusand is closely related to systemic inflammation.Malnutrition and inflammation decrease its synthesis.It has been shown that serum albumin levels areprognostic for breast cancer, and low albumin levelsare associated with decreased survival." (PMID 40386520, 2025). "Albumin level is a nutritional indicator and decreased levels are linked to malnutrition." (PMID 40231165, 2025). "According to multiple literature reviews, the factors contributing to malnutrition primarily include disease severity, body mass index (BMI), weight loss, age, food intake, gastrointestinal injury, albumin and hemoglobin levels, muscle mass, and inflammatory markers such as C-reactive protein (CRP)." (PMID 40611154, 2025). "Low levels of vitamin D, micronutrients, decreased albumin, and deficiency of antioxidants are among the key mechanisms through which malnutrition may contribute to the progression of frailty and cognitive impairment." (PMID 40871640, 2025).
malnutrition (continued). "The serum protein levels at the lower end of normal (6.0 ± 1.0 g/dL) and albumin (3.5 ± 0.5 g/dL) could have indicated acute-phase responses or underlying malnutrition." (PMID 40932962, 2025). "The results of the stratified analyses by BMI and serum albumin further support the hypothesis that malnutrition may partly explain the elevated risk observed in the lowest TyG quartile." (PMID 40764800, 2025). "The hypoalbuminemia resulting from low ALB may be associated with many different diseases, including cirrhosis, nephrotic syndrome and malnutrition." (PMID 40129577, 2025). "Chronic microinflammation, fueled by pro-inflammatory cytokines and oxidative stress, and malnutrition, arising from reduced intake, peritoneal albumin losses and inflammation itself, are strongly linked to adverse cardiovascular and infection outcomes, culminating in poor prognosis." (PMID 41348675, 2025). "While neutropenia rates were comparable between Candida and bacterial BSI cohorts, prior therapies, advanced disease, and significantly lower serum albumin levels indicated poorer functional status, malnutrition, frailty, and immune dysfunction as underlying risk factors for Candida BSI." (PMID 40175754, 2025). "Another study demonstrated not only low HbA1c to be associated with frailty, but also low body weight, low serum albumin, low Hb and low cholesterol, suggesting that malnutrition could be the underlying factor in this relationship." (PMID 40863223, 2025). "In addition, there was an increase in albumin concentration, which decreased the risk of malnutrition among the patients." (PMID 40094974, 2025). "Additionally, associations between low albumin and calcium levels in malnutrition affecting immunity were highlighted." (PMID 39760813, 2025). "In turn, the significantly reduced albumin level could be linked with malnutrition in the individuals with higher ploidy." (PMID 40002963, 2025). "Furthermore, the metabolic indicators in the RMH score, such as serum albumin, are closely related to sarcopenia, as sarcopenia itself is a syndrome associated with metabolic dysregulation and malnutrition." (PMID 40410709, 2025). "It has also been implicated in the promotion of anorexia, increased tissue catabolism, and a decreased synthesis rate of albumin, which together may drive the malnutrition, muscle decline, and weight loss characteristic of frailty." (PMID 40648869, 2025). "In cases where the AGR is low, this may be indicative of malnutrition or chronic disease, as lower albumin levels are commonly associated with a poorer nutritional status or inadequate protein synthesis." (PMID 40661684, 2025). "The hypoalbuminemia of patients on dialysis can be explained by a decrease in hepatic synthesis due to inflammatory processes that occur in patients with kidney failure or reflect malnutrition because of a decrease in protein‐calorie intake, or be secondary to albumin loss through the dialyzer." (PMID 40300783, 2025). "Univariate Cox regression analysis revealed several factors significantly associated with poor OS (all p < 0.05): AFP ≥ 400 ng/mL; malnutrition (both moderate and severe); serum albumin <35 g/L; maximum tumor diameter >5 cm; tumor number ≥3; and presence of MVI." (PMID 40642170, 2025). "Additionally, low cholesterol and albumin levels are associated with systemic inflammation, malnutrition, and liver dysfunction, and are thought to increase the risk of bleeding by disrupting haemostatic mechanisms." (PMID 41227038, 2025). "The present study also showed that an important part of vitamin D3 and albumin deficiency may be caused by malnutrition and impaired MF in the first place." (PMID 40863037, 2025). "Furthermore, any patient inthe ICU, an environment prone to infections, malnutrition, liver dysfunction, andrenal diseases, is susceptible to further albumin loss, disrupting fluid balance." (PMID 40776939, 2025).